IFNLR1 (interferon lambda receptor 1)
Diseases named in the same sentence as IFNLR1 in open-access papers (continued):
Sharing a sentence is not in itself a finding about the gene and the disease.
dementia (2 papers, 2022 to 2023). Loss of intellectual abilities interfering with an individual's social and occupational functions. "The study found an association with dementia of rs4918918 (SORBS1) and rs10903034 (IFNLR1) previously associated with suicide and confirmed the association of APOEε4 and APOEε2 with dementia." (PMID 36421848, 2022).
echovirus infection (2 papers, 2022 to 2026). "To dissect the relative contributions of type I and type III IFNs in protecting the liver during echovirus infection, we combined in vivo mouse models (expressing hFcRn and deficient in Ifnar1, Ifnlr1, or both) with single cell RNA sequencing (scRNA-seq)." (PMID 41592119, 2026).
fungal infections (2 papers, 2020 to 2022). "IFN-λ, acting via IFNLR1, has been shown to be important in the resolution of viral, bacterial, and fungal infections." (PMID 36379255, 2022).
reovirus infection (2 papers, 2015 to 2017). "In IEC preparations from Ifnlr1-/- mice that are highly susceptible to reovirus infection, induction of the Ifnl2/3 genes was nearly 100-fold higher than in infected wild-type mice, whereas type I IFN genes were not expressed at enhanced rates at this early time point." (PMID 25849543, 2015). "Nevertheless, these cells remained protected from reovirus in wild-type and Ifnlr1-/- mice, suggesting that type I IFN production during reovirus infection was low but protective." (PMID 25849543, 2015).
bronchiolitis (1 paper, 2022). Inflammation of the bronchioles characterized by swelling of the bronchioles and mucus accumulation. "In respiratory cells, our group detected elevated IFNLR1 expression in rhinovirus bronchiolitis in correlation with disease severity, but there are no previous in vivo studies conducted in cervical cells." (PMID 36422611, 2022).
chronic kidney disease (1 paper, 2023). Impairment of the renal function secondary to chronic kidney damage persisting for three or more months. "Additionally, single nucleotide polymorphisms in the IFNLR1 signaling pathway are linked to risk of chronic kidney disease." (PMID 37791586, 2023).
cognitive decline (1 paper, 2022). "Assessment of the relationship of SNPs, which are associated with the risk of suicide, with cognitive decline in older adults showed potential significance for rs4918918 in the SORBS1 gene and rs10903034 in the IFNLR1/IL10RB gene." (PMID 36421848, 2022).
Cryptosporidium infection (1 paper, 2023). "Indeed, type III IFNs show a profound protective role in control Cryptosporidium infection as mice lacking the type III receptor, Ifnlr1, showed an increase of parasite shedding following infection." (PMID 36928642, 2023).
diarrheal disease (1 paper, 2016). The condition of having at least three loose or liquid bowel movements each day. "In addition, in the current study weight loss and the degree of diarrheal disease were not substantially enhanced in Ifnlr1-/- and/or Stat1-/- mice when compared to WT suckling mice." (PMID 27128797, 2016).
Granuloma (1 paper, 2025). A compact, organized collection of mature mononuclear phagocytes, which may be but is not necessarily accompanied by accessory features such as necrosis. "The present study has shown the upregulation of IFNG and IFNLR1, included in the “interferon-mediated signaling pathway,” in patients with sarcoidosis with EPL manifestation, suggesting their potential role in granuloma progression to multiple organs." (PMID 41463010, 2025).
inflammatory bowel disease (1 paper, 2021). A spectrum of small and large bowel inflammatory diseases of unknown etiology. "Patients with inflammatory bowel disease (IBD) and mice with colitis demonstrate increased levels of IFNL and IFNLR1 compared with controls." (PMID 34899712, 2021).
malaria (1 paper, 2020). Malaria is a serious and sometimes fatal disease caused by a parasite that commonly infects a certain type of mosquito which feeds on humans. "As we had observed differences in plasma titers of antibodies in Ifnlr1−/- mice vs. littermate controls, we hypothesized that there would be differences in the early malaria-specific plasmablast response." (PMID 32407154, 2020).
parasitemia (1 paper, 2020). "Using flow cytometry to measure the percentage of erythrocytes containing parasites (parasitemia), we determined that parasitemia was strongly decreased in Ifnlr1−/- starting at day 10 post-infection when compared to littermate controls." (PMID 32407154, 2020).
pulmonary sarcoidosis (1 paper, 2025). Sarcoidosis affecting the lung parenchyma. "However, our study suggests that IFNLR1 upregulation in the PBMCs of patients with pulmonary sarcoidosis with EPL may relate to EPL development through PBMC recruitment to local lesions via circulation." (PMID 41463010, 2025). "Furthermore, the differential transcriptome features in PBMCs from patients with pulmonary sarcoidosis between patients with and without EPL were demonstrated, particularly the upregulations of IFNG and IFNLR1." (PMID 41463010, 2025).
sarcoidosis (1 paper, 2025). Sarcoidosis is a multisystemic disorder of unknown cause characterized by the formation of immune granulomas in involved organs. "In sarcoidosis, the IFNLR1 functions and regulatory mechanisms are yet to be fully elucidated." (PMID 41463010, 2025). "The upregulation of IFNG and IFNLR1 may be related to EPL development and could serve as potential therapeutic targets for sarcoidosis." (PMID 41463010, 2025).
infection (48 papers, 2010 to 2026). The state of being infected such as from the introduction of a foreign agent such as serum, vaccine, antigenic substance or organism. "This indicates that increased bacterial clearance seen during super-infection in global IFNLR1-/- mice is associated with enhanced IL-17 production." (PMID 39178311, 2024). "Accordingly, global IFNLR1-/- mice had significantly increased IL-17 and IL-22 in the airways, and neutralization of IL-17A during infection caused significantly increased bacterial burden compared to untreated mice." (PMID 39178311, 2024). "Multiple ISGs were significantly reduced in IFNLR1-KO cells vs. control lines despite expressing moderately higher levels of viral mRNA, suggesting an increased susceptibility to infection." (PMID 34899695, 2021). "WT mice were treated intranasally with identical doses of IFN-α or IFN-λ one day before infection with SeV and co-housed with Ifnar1−/− Ifnlr1−/− double-deficient sentinel mice." (PMID 29651984, 2018). "As such, relative expression of IFNLR1 variants in IFNL-unexposed cells could contribute to the constitutive balance of ISG expression in cells prior to infection and IFNL exposure." (PMID 41256602, 2025). "However, several other parameters measuring super-infection severity, including lung leak, weight loss, and immune cell recruitment to the airways, remained unchanged between WT and global IFNLR1-/- mice at both 6 and 24 hours post-bacterial infection." (PMID 39178311, 2024). "While the specific molecules driving IL-17 production during super-infection are still unclear, our results suggest that enhanced bacterial clearance in global IFNLR1-/- mice is associated with a more robust type 17 response, which is likely not regulated by one molecule alone." (PMID 39178311, 2024). "When the infection was initiated by applying the inoculum selectively to the upper airways, none of the influenza viruses used in this study caused morbidity or mortality, although virus titers in lungs of Ifnlr1−/− mice reached levels above 106 PFU in some animals on day five post-infection." (PMID 29651984, 2018). "Interestingly, on day 4 post-infection the vast majority of infected cells in Ifnar1-/- mice were located in the lamina propria region and not the epithelium as on day 1, whereas virus antigen remained associated with IECs in Ifnlr1-/- mice." (PMID 25849543, 2015). "Our cellular analysis of the immune response revealed an increase in CD8 T cell–priming CD103+ DC in the lungs of Ifnlr1–/– mice compared with WT on day 4 after infection (p.i.)." (PMID 38973611, 2024). "To assess the link between tuft cell infection and viral diversity, we treated WT and Ifnlr1-/- mice with two doses of recombinant IL-4." (PMID 38701091, 2024). "We administered IL-4 to mice prior to infection, a treatment well-established to enhance intestinal tuft cell numbers, and found that this enhanced infection and barcode richness in WT and Ifnlr1-/- mice." (PMID 38701091, 2024). "We employed inducible CX3CR1-specific conditional IFNLR1 knockout mice to determine if IFNλ acts directly on these cells during super-infection." (PMID 39178311, 2024). "CD163+Erg2+ M2 macrophages were reduced on day 1 post-infection in WT and Ifnlr1−/− mice but present in Ifnar1−/− mice, suggesting type I IFN drives depletion of M2 macrophages early post-infection." (PMID 38530032, 2024). "To do this, we used a multiplex bead-based immunoassay of mouse lung homogenates in WT, Ifnar1−/−, and Ifnlr1−/− mice day 1 post-infection." (PMID 38530032, 2024). "We also observed a potential modulatory role for IFN-λ in HMPV disease, as Ifnlr1−/− mice showed higher expression of inflammatory cytokines and ISGs early post-infection." (PMID 38530032, 2024).
infection (continued). "Here, we examined activation of antibacterial immune responses including bacterial uptake and phagolysosomal localization during super-infection in IFNLR1-/- and wild type (WT) mice to demonstrate direct effects of IFNλ signaling on phagocytes." (PMID 39178311, 2024). "We found that the increased intestinal viral replication seen in Ifnlr1-/- mice was associated with a substantial increase in barcode richness, supporting that IFN-λ serves to limit initial tuft cell infection events and therefore overall viral diversity." (PMID 38701091, 2024). "The IFNAR/IFNLR1 KO A549 cells enable the analysis of both IFN types on cellular metabolism during USUV infection." (PMID 35186796, 2022). "These co-staining data are consistent with early mRV evasion of IFN responses within infected IECs at the same timepoints that we observed increased infection of Ifnlr1 IEC-cKO mice." (PMID 35137688, 2022). "Further, in macrophages, IFNLR1 was necessary for a robust ISG response to direct infection and was entirely responsible for ISGs produced in response to secreted interferon." (PMID 34899695, 2021). "We demonstrate that macrophage IFNLR1 is necessary for the induction of ISGs in response to both direct infection and in response to secreted factors from neighboring infected cells." (PMID 34899695, 2021). "In a murine model of influenza A viral (IAV) infection Ifnlr1 mRNA expression on DCs increased following infection, which correlated with increased IFNγ and tumor necrosis factor (TNF) production by lung CD8+ T cells." (PMID 34899712, 2021). "Interferon lambda receptor 1 (IFNLR1) is a cytokine that regulates infection in the liver, brain, and gastrointestinal tract in mice." (PMID 34439958, 2021). "Serum ALT elevations were comparable in the two types of mice at days 7 and 14 p.i., but HAV RNA levels in both liver and feces were significantly greater in the Ifnlr1-/-Ifnar1-/- mice than Ifnar1-/- mice on day 14 post-infection." (PMID 34591933, 2021). "Titers of anti-MSP1 IgG2 c and IgM were increased at day 7 post-infection in Ifnlr1−/- mice vs. littermate controls." (PMID 32407154, 2020). "Of note, only small changes in expression of Il10rb were observed between days 0 and 7, whereas Ifnlr1 mRNA was time-dependent, with the highest expression occurring on days 1 and 4 after infection." (PMID 30655513, 2019). "Our preceding data demonstrated that disrupting CR6 NS1/2 cleavage prevented early infection of intestinal tissues and consequent persistent shedding in feces of either WT or Ifnlr1-/- mice." (PMID 31329638, 2019). "Ifnlr1−/− mice showed increased BBB permeability after infection, and IFN-λ treatment enhances colocalization of endothelial junction proteins, ZO-1 and claudin-5 to increase BBB tightness." (PMID 29361691, 2018). "In contrast, SeV reached the lungs of WT mice at significantly reduced frequency (6/15) under these experimental conditions, and virus titers at day five post-infection in the lungs of WT mice were generally lower compared with Ifnlr1−/− mice." (PMID 29651984, 2018). "When the nostrils of SeV-infected mice were swabbed, we found at least 10-fold more infectious SeV in mucosal secretions of Ifnlr1−/− mice compared with WT controls between days 2 and 4 post infection." (PMID 29651984, 2018). "Accordingly, Ifnlr1−/− animals exhibit markedly enhanced viral burden following infection with low viral load and upregulated type I IFN levels, highlighting the essential role IFNλs play in these processes." (PMID 29033947, 2017). "We observed virtually identical fecal shedding of EW-RV in WT, Ifnlr1-/-, Ifnar1-/-, Ifnar1-/-Ifnlr1-/- or Stat1-/- mice during the first 7 days post infection (dpi)." (PMID 27128797, 2016). "Immunohistochemistry revealed heavy infection of IECs in the terminal small intestine and colon of Ifnlr1-/- mice, whereas the virus was largely localized to the lamina propria region of the small intestine in Ifnar1-/- mice." (PMID 25849543, 2015).
infection (continued). "By day 4 post-infection, wild-type animals had largely cleared the virus, whereas the intestinal tissue of Ifnar1-/- and Ifnlr1-/- mice was still heavily positive for reovirus antigen." (PMID 25849543, 2015). "Two-days-old wild-type, Ifnlr1-/- and Ifnar1-/- animals were orally infected with reovirus, and viral titers in small intestine and colon were analyzed on day 4 post-infection." (PMID 25849543, 2015). "Accordingly, reovirus replication in the terminal small intestinal tissue at day 4 post-infection was significantly higher in Ifnar1-/- mice compared to Ifnlr1-/- or wild-type animals." (PMID 25849543, 2015). "Reovirus antigen was almost exclusively found in IECs of Ifnlr1-/- mice at day 4 post-infection, whereas reovirus was restricted to lamina propria cells in Ifnar1-/- mice." (PMID 25849543, 2015). "H&E staining of the liver tissue on day 4 post-infection revealed inflammatory cells in all reovirus-infected animals with infiltrates localized predominantly around intrahepatic bile ducts in Ifnlr1-/- mice." (PMID 25849543, 2015). "We found that during acute infection, most barcodes were shared between colon, ileum, and stool in both WT (~33%) and Ifnlr1-/- mice (~74%), suggesting initial infection events in the intestine contribute to both fecal shedding and infection along the gastrointestinal tract." (PMID 38701091, 2024). "However, by day 5 post-infection, 11 of 16 (69%) Ifnlr1−/− mice tested showed HMPV spread to lower airways." (PMID 38530032, 2024). "Global IFNLR1-/- mice had significantly reduced bacterial burden versus WT mice at 24 hours post-bacterial infection, with a trend apparent as early as 6 hours post-infection." (PMID 39178311, 2024). "Measurement of chemokines in the lung showed several alterations in global IFNLR1-/- mice compared to WT mice both during super-infection and single S. aureus infection, including increased TNFα, CXCL11, CXCL12, and MIP3α and decreased IL-1β, MIP1β, and CXCL16." (PMID 39178311, 2024). "This correlated with an increase in virus titers in Ifnlr1–/– early in infection compared with WT." (PMID 38973611, 2024). "We assessed an earlier timepoint at 12 hr post-inoculation and observed similar trends toward an increased proportion of IEC infection in Ifnlr1 IEC-cKO relative to Ifnlr1flox/flox littermates, but the extent of infection was 10- to 100-fold lower and near the limit of detection." (PMID 35137688, 2022). "In addition, we found that a threefold greater proportion of IECs were infected with mRV in Ifnlr1 IEC-cKO mice than Ifnlr1flox/flox mice at 24 hr post-infection." (PMID 35137688, 2022). "However, mice lacking TLR3 were more susceptible, resulting in an 8-fold increase in parasite shedding and an overall pattern of infection that was reminiscent of Ifnlr1-/- mice (AUC, Standard t-test * p <0.05)." (PMID 35584177, 2022). "We again added a blocking anti-Ifnar1 mAb to OVX WT and Ifnlr1−/− mice to facilitate infection." (PMID 30655513, 2019). "Importantly, Ifnar1−/− mice shed significantly less virus than Ifnlr1−/− mice at all time points between days 2 and 4 post infection, indicating that IFN-λ is the dominant limiting factor for virus shedding." (PMID 29651984, 2018). "Already at 12 hr post infection, Ifnlr1−/− mice secreted remarkable amounts of infectious virus." (PMID 29651984, 2018). "Given the different functions of type I IFN vs IFN-λ in HMPV infection, we next tested whether this correlated to differences in lung innate immune cell recruitment by flow cytometry of lung cells in mock- vs HMPV-infected WT, Ifnar1−/−, and Ifnlr1−/− mice early post-infection." (PMID 38530032, 2024). "To determine whether the oily hair syndrome, observed in infected Ifnlr1-/- mice, was due to preferential replication of reovirus in biliary epithelial cells, we stained the liver and extrahepatic biliary tubules for virus antigen at day 4 post-infection." (PMID 25849543, 2015).